JAG2 (jagged canonical Notch ligand 2)
Diseases named in the same sentence as JAG2 in open-access papers (continued):
Sharing a sentence is not in itself a finding about the gene and the disease.
muscular dystrophy (6 papers, 2016 to 2026). Muscular dystrophy (MD) refers to a group of more than 30 genetic diseases characterized by progressive weakness and degeneration of the skeletal muscles that control movement. "Binding sites for hnRNP L have been noted on the mRNA of JAG2, which encodes a canonical Notch ligand and muscular dystrophy gene." (PMID 40944391, 2026). "Specific components of the Notch pathway, namely ligands Jag1 and Jag2, have been implicated in the dysfunction seen in muscular dystrophy." (PMID 36237531, 2022). "This suggests that the molecular mechanism of the muscular dystrophy caused by JAG2 mutations overlaps with that underlying EMARDD, and also argues for JAG2 as a putative gene modifier in MEGF10-myopathy." (PMID 34740639, 2022). "We previously identified a muscular dystrophy caused by biallelic variants in JAG2, whose protein product Jagged2 JAGGED2 (JAG2) is a canonical Notch NOTCH ligand." (PMID 42154534, 2026). "Our findings indicate that optimizing JAG2-mediated NOTCHNotch signaling is a potential therapeutic approach for JAG2-related muscular dystrophy." (PMID 42154534, 2026). "Currently, three muscle disease genes that interact with the Notch pathway have recently been identified—Jag2, MEGF10, and POGLUT1—whose mutation has been noted in muscular dystrophies." (PMID 36237531, 2022). "Therefore, we hypothesize that MCK-N1ICD upregulates Dll4/Jag2 in myofibers, which in turn activates Notch signaling in juxtaposed SCs to regulate their self-renewal in response to aging and muscular dystrophy." (PMID 27644105, 2016).
pancreatic cancer (6 papers, 2013 to 2022). "Mullendore and coauthors observed overexpression of Notch ligands, predominantly Jag2 and Dll4 that were observed in 90% and 50% pancreatic cancer cell lines, respectively." (PMID 32211044, 2020). "Likewise, tRF/miR-1280 was also found to be critical in pancreatic cancer by significantly decreasing JAG2 in pancreatic cancer derived cell lines such as HCT116, HCT15, and Panc-1 cells, at protein level." (PMID 36072340, 2022). "Notably, blockade of the ligand–receptor interaction by a JAG2‐Fc fusion protein could inhibit the migration of pancreatic cancer cells." (PMID 32250571, 2020). "Study has previously demonstrated depletion of JAG2 gene intensely inhibited pancreatic cancer cell migration, invasion and metastasis without influencing cell proliferation." (PMID 32792862, 2020).
adenoma (5 papers, 2005 to 2020). A neoplasm arising from the epithelium. "Comparatively, in adenomas, ≥2-fold Notch3 expression was detected in 56% followed by Notch1 (44%), Notch4 (33%), and Notch2 (11%), while for ligand Jag1, mRNA was overexpressed in 33%, Jag2, Dll1, and Dll3 in 11%, whereas Dll4 was not expressed in adenomas." (PMID 32211044, 2020).
metastatic disease (4 papers, 2017 to 2025). "Our data suggest that inhibition of Notch3 signaling, and in particular, the Jag2/Notch3/Hey1 axis may be an effective therapy for HNSCC metastatic disease." (PMID 37202533, 2023). "COL3A1, COL5A2, VCAN, CCND2, JAG2, and VTN showed consistent positive correlations with all three scores in both primary and metastatic tumors, suggesting their involvement in enhancing stromal support and recruiting immune cells." (PMID 40943183, 2025).
cleft palate (3 papers, 2013 to 2019). Cleft palate is a fissure type embryopathy that affects the soft and hard palate to varying degrees. "The ChIP-seq data also identified p63-bound regions associated with Pvrl1, Irf6, Fgfr2, Tcfap2a, Pdgfa, Sfn, Grhl3 and Jag2, mutations in which result in cleft palate." (PMID 28604778, 2017). "The first evidence showing that JAG2 may be related to oral clefting came from animal studies, where Jag2 knockout mice die at birth due to completely penetrant cleft palate." (PMID 23524414, 2013).
endometrial cancer (3 papers, 2019 to 2022). Primary or metastatic malignant neoplasm involving the endometrium (mucous membrane that lines the endometrial cavity). "Collectively, these data show that JAG2, AURKA, PGK1, and HRPT1 have the potential to be used independently as diagnostic, prognostic, or treatment biomarkers in endometrial cancer." (PMID 30679932, 2019). "They proposed that the jagged canonical Notch ligand 2 (JAG2), Aurora kinase A (AURKA), phosphoglycerate kinase 1 (PGK1), and hypoxanthine phosphoribosyltransferase 1 (HRPT1) could be used independently as diagnostic, prognostic, or treatment biomarkers in endometrial cancer." (PMID 34322276, 2019). "We have determined that there is a significant elevation of JAG2, HPRT1, AURKA, and PGK1 expression in endometrial cancer." (PMID 30679932, 2019).
liver cancer (3 papers, 2015 to 2024). An epithelial or non-epithelial malignant neoplasm that arises from the liver. "The down-regulated tumor suppressor miR-2392 directly targets Jagged 2 (JAG2) overexpression and promotes the malignant progression of liver cancer." (PMID 38808545, 2024).
medulloblastoma (3 papers, 2014 to 2019). A malignant, invasive embryonal neoplasm arising from the cerebellum. "It was found in a recent study that the expression of JAG2 protein is elevated in metastatic medulloblastoma tissues and associated with a poor prognosis, and the proliferation rate and migration ability of medulloblastoma cell lines are reduced by siRNA-mediated JAG2 gene silence." (PMID 31198409, 2019).
pancreatic adenocarcinoma (3 papers, 2020 to 2024). "MiRNA-876-3p exerts inhibitory effects on pancreatic adenocarcinoma cell growth and metastasis through regulating JAG2." (PMID 37426414, 2023). "For example, miR-605-5p was markedly downregulated in melanoma tissues and cells and inhibited melanoma progression and glutamine catabolism through targeting GLS; miR-876-3p functioned as a tumor suppressor and correlated with cell metastasis in pancreatic adenocarcinoma via targeting JAG2." (PMID 33363164, 2020). "JAG2 is a canonical ligand of Notch signaling, which functions as a regulator of physiological processes such as cell differentiation and an oncogene in many tumors such as HCC and pancreatic adenocarcinoma." (PMID 38395762, 2024).
uveal melanoma (3 papers, 2019 to 2023). A melanoma derived from melanocytes of the uveal tract. "To verify our computational findings, we tested the mRNA expression level of CCL18, CXCL8, GTPBP1, JAG2, PRELID1 and PTGER4 in uveal melanoma cell lines: M17, M23 and SP6.5 and normal uveal epithelial cell: Um95." (PMID 36597071, 2023).
B-cell chronic lymphocytic leukemia (2 papers, 2020 to 2022). "Notch 1, Notch 2 and their ligands Jag1 and Jag2 are constitutively expressed in B-cell chronic lymphocytic leukemia (CLL) and confer resistance to apoptosis in malignant B-cells." (PMID 33374160, 2020). "In B-cell chronic lymphocytic leukemia (B-CLL), NOTCH1, NOTCH2, and their ligands (JAG1 and JAG2) are constitutively expressed." (PMID 35335147, 2022). "Rosati E and co-workers demonstrated a high expression of Notch 1, Notch 2, JAG1 and JAG2, in malignant B-cells isolated from 25 patients affected by B-cell chronic lymphocytic leukemia (B-CLL) but not in normal B-cells." (PMID 33374160, 2020).
colorectal tumors (2 papers, 2017 to 2019). "Kaplan Meier survival curve showed the expression of HLAB, 14-3-3β, ADAMTS2, LTBP3, NME2 and JAG2 on colorectal tumour cells associated with CRC specific survival." (PMID 30679934, 2019). "We recently reported that JAG2 expression is up-regulated in colorectal tumors of ApcCKO mice resulting from transduction of colonic epithelium with Cre-encoding lentivirus." (PMID 28881809, 2017). "We previously have shown that JAG2 expression is increased in colorectal tumors of ApcCKO mice." (PMID 28881809, 2017). "In addition, a high-level expression of JAG2, one of the NOTCH ligands, was also observed in the colorectal tumors of ApcCKO mice, suggesting the role of JAG2 in colorectal tumorigenesis." (PMID 28881809, 2017).
glioma (2 papers, 2013 to 2015). A benign or malignant brain and spinal cord tumor that arises from glial cells (astrocytes, oligodendrocytes, ependymal cells). "Seventeen genes represent active Notch signaling components, including NOTCH1, NOTCH3, HES1, MAML1, DLL-3, and JAG2, which are enriched in the proneural subtype of glioma stem cells." (PMID 26599017, 2015).
intervertebral disc degeneration (2 papers, 2019 to 2022). "Previously, JAG2/Notch2 axis has been reported to alleviate intervertebral disc degeneration (IVDD) by modulating apoptosis, proliferation, and the extracellular matrix of nucleus pulposus cells." (PMID 36035989, 2022).
liver fibrosis (2 papers, 2021 to 2024). "After screening the well-defined signaling involved in the pathogenesis of liver fibrosis, we clarified that miR-541 suppressed Notch signaling by targeting JAG2." (PMID 38395762, 2024). "Dysregulation of miR-541/JAG2 axis might be a as a new mechanism of liver fibrosis, and miR-541 could serve as a novel non-invasive biomarker and therapeutic targets for liver cirrhosis." (PMID 38395762, 2024). "As a key component of the Notch cascade, the role of JAG2 in hepatic fibrosis has not been reported." (PMID 38395762, 2024). "Although the Notch signaling pathway has been reported to play an important role in liver fibrosis, the function of JAG2 on the activation of HSCs has not yet been reported." (PMID 38395762, 2024).
neuroblastoma (2 papers, 2016 to 2017). Neuroblastoma (NB) is the most common solid, extracranial childhood tumor. "Since PI3KC2β is known to play a role in neuroblastoma tumorigenesis, its suppression might contribute to the potent inhibitory effects that we observed on growth and clonogenicity upon suppressing Jag2 in both retinoblastoma lines." (PMID 27661116, 2016). "Since PI3KC2β is known to play a role in neuroblastoma tumorigenesis, by promoting Akt activity, its downregulation might be at least in part responsible for the potent inhibitory effect on growth and clonogenicity that we observed after suppressing Jag2 in both retinoblastoma lines." (PMID 27661116, 2016).
non-small cell lung carcinoma (2 papers, 2021). A group of at least three distinct histological types of lung cancer, including non-small cell squamous cell carcinoma, adenocarcinoma, and large cell carcinoma. "Moreover, JAG2 inhibited monocyte recruitment by reducing the expression of inflammation-related genes in human non-small cell lung cancer cells." (PMID 33781349, 2021). "In particular, the cell treatment was associated with the up-regulation of NOTCH1, JAG2, coding for Notch-ligand Jagged-2 protein, and MMP2, coding for matrix metalloprotease 2, an invasion-facilitating collagenase which is a prognostic factor for non-small cell lung cancer." (PMID 34198869, 2021).
osteosarcoma (2 papers, 2021 to 2024). A usually aggressive malignant bone-forming mesenchymal neoplasm, predominantly affecting adolescents and young adults. "Similarly, several survival-related genes, including MUC1, COL13A1, KAZALD1, and JAG2, were identified as prognostic markers in osteosarcoma by scRNA-seq and TARGET analysis." (PMID 39324133, 2024). "Moreover, Jag2 and Notch4 are highly expressed in some murine osteosarcomas, and NOTCH3 has somatic copy-number alterations in about 10% of human osteosarcoma samples." (PMID 34439353, 2021).
pulmonary arterial hypertension (2 papers, 2023 to 2024). Pulmonary arterial hypertension (PAH) is a group of diseases characterized by mean pulmonary artery pressure >20 mmHg and elevated pulmonary arterial resistance leading to right heart failure. "Adeno-associated virus-mediated Jag2 inhibition was used to explore the role of Jag2 in peripheral pulmonary vascular remodeling assessed in a rat model of chronic hypoxia (10% O2, 4 weeks) induced pulmonary hypertension." (PMID 38277398, 2024).
rectal cancer (2 papers, 2020 to 2023). A primary or metastatic malignant neoplasm that affects the rectum. "Furthermore, TRF/mir-1280 inhibits the 3ʹ-UTR of JAG2, reduces JAG2 biosynthesis, inhibits the Notch pathway, and directly inhibits the migration and epithelial–mesenchymal transition (EMT) of rectal cancer cells." (PMID 37480078, 2023).
retinoblastoma (2 papers, 2016 to 2019). A malignant tumor that originates in the nuclear layer of the retina. "We used Ingenuity® Pathway Analysis (IPA®) to determine the top signaling pathways modulated by the genes that we found to be overexpressed or downregulated in the retinoblastoma cells where Jag2 was inhibited." (PMID 27661116, 2016). "Notch pathway components were present in WERI Rb1 and Y79 retinoblastoma lines, with Jag2 and DLL4 more highly expressed than other ligands, and Notch1 and Notch2 more abundant than Notch3." (PMID 27661116, 2016). "Interestingly, Jag2 mRNA and protein levels were much higher in both retinoblastoma lines as compared to Jag1, which was barely measurable by both Western blot and qPCR." (PMID 27661116, 2016). "Since we observed that Jag2 mRNA and protein levels were more elevated than Jag1 in both retinoblastoma lines, and also upregulated compared to normal adult retina, we decided to also genetically inhibit Notch signaling by downregulating expression of this Notch ligand." (PMID 27661116, 2016). "Upregulation of the cytokine receptor pathway was also observed when we combined the gene expression data from both retinoblastoma lines after Jag2 suppression, raising the possibility that this pathway might also play a role in promoting retinoblastoma growth downstream of Notch." (PMID 27661116, 2016).
Anxiety (1 paper, 2017). Intense feelings of nervousness, tension, or panic often arise in response to interpersonal stresses. "We previously reported anxiety-related differential methylation of JAG1 and JAG2 in the central nucleus of the amygdala of young monkeys;26 here we find anxiety-related differential methylation of JAG2 in humans." (PMID 29225348, 2017).
autosomal recessive limb-girdle muscular dystrophy-27 (1 paper, 2023). "Finally, homozygous and compound heterozygous mutations in JAG2 are identified families that have autosomal recessive limb-girdle muscular dystrophy-27, which suggests a disease mechanism that is related to Notch pathway dysfunction." (PMID 36833423, 2023).
bladder tumor (1 paper, 2020). "These evidences suggested that JAG2/Jgged2 could play an important role on bladder tumor proliferation and invasion." (PMID 32792862, 2020). "Additionally, silenced Notch/JAG2 gene of BC cells, regardless of Mel treatment, was superior to Mel treatment for inhibiting the PI3K/AKT/mTOR signaling pathway, which in turn, suppressed the bladder tumor growth." (PMID 32792862, 2020).
clear cell ovarian cancer (1 paper, 2020). "The high JAG2+TANs densities indicated poor clinical outcomes in patients with both serous and clear cell ovarian cancer." (PMID 32778818, 2020).
colon adenocarcinoma (1 paper, 2017). "To further analyze the role of JAG2 in the tumorigenicity of CRC cells, we generated MC38 cells, a cell line derived from mouse colon adenocarcinoma, that constitutively express JAG2 using lentivirus." (PMID 28881809, 2017).
colorectal adenoma (1 paper, 2020). An adenoma that arises from the colon or rectum. "We investigated mRNA expression of four Notch receptors (Notch1–4), five ligands (Jag1, Jag2, Dll1, Dll3, and Dll4), and four target genes (Hes1, Hes5, Hey1, and Hey2) using highly specific TaqMan gene expression assays in colorectal adenomas and cancers." (PMID 32211044, 2020).
cylindromas (1 paper, 2014). "Normal skin exhibited undetectable levels of JAG2 compared to 5 cylindromas and one spiradenoma, even when enhanced amounts of normal skin protein were assessed in western blots." (PMID 25565632, 2014).
diffuse large B-cell lymphoma (1 paper, 2025). "A comparable trend was observed in the DLBC (diffuse large B-cell lymphoma) dataset, where Usp11 and JAG2 displayed a correlation." (PMID 39904982, 2025).
endometriosis (1 paper, 2019). The growth of functional endometrial tissue in anatomic sites outside the uterine body. "The expression of JAG1 was increased from proliferative into secretory phase, which proposes a responsibility for JAG1 in the endometrial receptivity, and the endometrial expression of JAG2 was decreased in endometriosis, which is contributed to the decidualization failure." (PMID 31168348, 2019). "Inconsistently, the current study demonstrated that NOTCH1, JAG-1, JAG-2, and survivin, as a down target molecule of NOTCH pathway, significantly decrease in women with PCOS, endometriosis, and RIF." (PMID 31168348, 2019). "Western blot analysis showed a significantly lower JAG1 and JAG2 protein expression in the endometrial samples of PCOS patients, and endometriosis and RIF groups compared with the healthy fertile ones." (PMID 31168348, 2019). "Furthermore, JAG2 gene expression was significantly down-regulated in the endometrium of PCOS (P<0.0001), endometriosis (P<0.05), and RIF (P<0.0001) groups compared with control subjects." (PMID 31168348, 2019).
fetal growth restriction (1 paper, 2015). A fetus that does not grow beyond the 10th percentile of conventionally accepted weight for gestational age. "A significant decrease in the immunoreactivity of NOTCH2 and JAG2 proteins has been observed before in human term placentas complicated by fetal growth restriction (FGR) or hypertension, compared to normal placentas." (PMID 25962154, 2015).
Insulin resistance (1 paper, 2019). Increased resistance towards insulin, that is, diminished effectiveness of insulin in reducing blood glucose levels. "J 2 (JAG2), NOTCH3, CDKN1A, HES1, and MAPT are novel biomarkers for the development of insulin resistance." (PMID 30678306, 2019).
intestinal tumors (1 paper, 2017). "Among all the members of NOTCH ligands, only the expression of JAG2 was found up-regulated in the intestinal tumors of ApcMin/+ mice as compared to the nearby normal mucosa." (PMID 28881809, 2017). "To determine JAG2 expression in other mouse models of CRC, we analyzed JAG2 expression in the intestinal tumors of ApcMin/+ mice." (PMID 28881809, 2017). "Immunohistochemical analysis revealed that the expression of JAG2 and HES1, a downstream target of NOTCH signaling, was increased in the intestinal tumors of ApcMin/+ mice." (PMID 28881809, 2017). "JAG2-induced increase in reporter activity was suppressed by DAPT, a γ-secretase inhibitor, suggesting that the expression of JAG2 may contribute to the activation of NOTCH signaling in intestinal tumors." (PMID 28881809, 2017).
liver cirrhosis (1 paper, 2024). "To confirm that JAG2 was a functional target of miR-541 in liver cirrhosis, we first evaluated the correlation of JAG2 expression and fibrosis marker and found that JAG2 expression was negatively correlated with Col1a levels." (PMID 38395762, 2024). "This indicates that JAG2 is a direct target of miR-541 in liver cirrhosis." (PMID 38395762, 2024).